KCNJ18 (potassium inwardly rectifying channel subfamily J member 18)
Description:
Inward rectifier potassium channels are characterized by a greater tendency to allow potassium to flow into the cell rather than out of it. Their voltage dependence is regulated by the concentration of extracellular potassium; as external potassium is raised, the voltage range of the channel opening shifts to more positive voltages. The inward rectification is mainly due to the blockage of outward current by internal magnesium.
Synonyms: KIR2.6; TTPP2
Tractability: Antibody: UniProt places it where antibodies can reach, with high confidence; its Gene Ontology location is reachable by antibodies, with high confidence; UniProt predicts a signal peptide or a membrane-spanning region.
Gene: Protein-coding gene on chromosome 17 (21,692,523 to 21,704,612, forward strand). Ensembl gene ENSG00000260458.
Subcellular location: Cell membrane; Endoplasmic reticulum
Subcellular location (Human Protein Atlas): Golgi apparatus; Cytosol; Nucleoplasm
Gene Ontology:
Molecular function: inward rectifier potassium channel activity; protein binding
Biological process: potassium ion import across plasma membrane; potassium ion transport
Cellular component: endoplasmic reticulum; plasma membrane; membrane
Genetic constraint (gnomAD): Loss-of-function variants: 21 observed, 16.73 expected, observed/expected ratio (o/e) 1.26, 90% interval 0.89 to 1.77. The upper end of that interval is the gene's LOEUF score, 1.77, which puts it in group 6 of 6, group 1 being the genes least tolerant of losing a copy. Missense variants: 463 observed, 481.91 expected, observed/expected ratio (o/e) 0.96, 90% interval 0.89 to 1.04. Synonymous variants: 186 observed, 187.57 expected, observed/expected ratio (o/e) 0.99, 90% interval 0.88 to 1.12.
Homologues: Orthologues: macaque KCNJ12 (98% identical), guinea pig Kcnj12 (97% identical), dog KCNJ12 (96% identical), rat Kcnj12 (95% identical), mouse Kcnj12 (95% identical), tropical clawed frog kcnj12 (81% identical), zebrafish kcnj12a (79% identical), zebrafish kcnj12b (71% identical). Paralogues in human: KCNJ12 (99% identical), KCNJ2 (70% identical), KCNJ4 (65% identical), KCNJ14 (56% identical), KCNJ9 (45% identical), KCNJ3 (44% identical), KCNJ5 (44% identical), KCNJ6 (44% identical), KCNJ11 (40% identical), KCNJ8 (40% identical), KCNJ16 (39% identical), KCNJ1 (38% identical), and 3 more.
Diseases named in the same sentence as KCNJ18 in open-access papers:
KCNJ18 is named in the same sentence as 29 diseases in open-access papers, as found by Europe PMC text mining. Sharing a sentence is not in itself a finding about the gene and the disease. The quoted sentences say what the papers report.
hyperthyroidism (3 papers, 2015 to 2025). Overactivity of the thyroid gland resulting in overproduction of thyroid hormone and increased metabolic rate. "The follow-up period (2–35 months) in patients without KCNJ18 variants showed that episodic weakness did not recur after remission of hyperthyroidism." (PMID 25885757, 2015).
thyrotoxic periodic paralysis (3 papers, 2022 to 2025). Thyrotoxic periodic paralysis (TPP) is a rare neurological disease characterized by recurrent episodes of paralysis and hypokalemia during a thyrotoxic state. "Variants in the KCNJ18 gene have been found to be associated with thyrotoxic periodic paralysis-2 (TTPP2), but its haploinsufficiency association with the clinical phenotypes is yet to be identified." (PMID 37260775, 2023). "Three variants (R39Q, R40H, I249V) in the KCNJ18 gene were previously reported, and they are related to thyrotoxic periodic paralysis (TPP)." (PMID 35456240, 2022).
channelopathies (1 paper, 2025). "Variants in inward-rectifier potassium channels such as Kir2.6 (encoded by KCNJ18) and related channelopathies have been reported in case-control and family studies, although findings are not uniform across populations, and such variants are neither necessary nor sufficient for TPP." (PMID 41523487, 2025).
tumor (3 papers, 2019 to 2025). "Alterations in FCGBP, FLG, KCNJ12, and KCNJ18 were observed in all tumor samples." (PMID 37182141, 2023). "First, alterations in FCGBP, FLG, KCNJ12, and KCNJ18 were observed in all tumor samples, regardless of the responsiveness towards HIPEC." (PMID 37182141, 2023).
cancer (2 papers, 2022 to 2023). A tumor composed of atypical neoplastic, often pleomorphic cells that invade other tissues. "In the 8-mRNA signature (KCNJ18, RPE65, GRIA1, LCN15, C11orf21, ANXA13, FSIP2 and KRT76), the expressions of some mRNAs have been reported to have significant associations with the survival in some cancers." (PMID 35675043, 2022).
KCNJ18 also shares sentences with these, for which no sentence is quoted: periodic paralysis (3 papers); thyrotoxicosis (2); Andersen-Tawil syndrome (1); Arrhythmia (1); cervical cancer (1); fibromuscular dysplasia (1); Graves disease (1); Holt-Oram syndrome (1); Hyperinsulinemia (1); Hypokalemia (1); Hyporeflexia (1); keratoconus (1); macular degeneration (1); MODY (1); muscular dystrophy (1); neuropathy (1); non-melanoma skin carcinoma (1); pancreatic adenocarcinoma (1); pancreatic cancer (1); paraplegia (1); prostate carcinoma (1); retinopathy (1); spinal muscular atrophy (1); type 1 diabetes mellitus (1).